SOX2 (SRY-box transcription factor 2)
Diseases named in the same sentence as SOX2 in open-access papers (continued):
Sharing a sentence is not in itself a finding about the gene and the disease.
ovarian carcinoma (continued). "Applied to six cancer types including renal, breast, pancreatic, head and neck, colorectal, and ovarian cancers, TeaCNV delineated polyclonal architectures and revealed distinct chromatin accessibility patterns driven by CNVs in key driver genes, including AKT2, ZNF217, and SOX2." (PMID 42202285, 2026). "To understand whether macrophages are influencing CSCs and SOX2 expression, as our in vitro models would suggest, we profiled CD117+, CD133+, and ALDH+ ovarian cancer cells and changes in SOX2 protein expression in the resected tumors from the different treatment groups." (PMID 39287565, 2024). "Ovarian cancer cells treated in vitro with CCL2/MCP-1 and carboplatin significantly increased spheroid formation ability and increased SOX2 expression, suggesting that CCL2/MCP-1 could be one of the secreted factors from macrophages during chemotherapy that supports CSC features." (PMID 39287565, 2024). "Additionally, CHI3L1(YKL40) has a significant impact on the generation of ovarian cancer stem cells by activating the Akt and ERK signaling pathways to promote the expression of β-catenin and SOX2, thus endowing ovarian cancer cells with characteristics of cancer stem cells." (PMID 38543093, 2024). "Our collective results provide new insight into mechanisms that upregulate ST6Gal-I expression in ovarian cancer cells, and also point to the possibility that some of the CSC characteristics commonly attributed to Sox2 may, in part, be mediated through the sialyltransferase activity of ST6Gal-I." (PMID 31610800, 2019). "RAD6 is overexpressed in HGS-OvCa and its levels strongly correlate with ovarian cancer progression; in ovarian cancer cells RAD6 stabilizes beta-catenin promoting stem cell-characteristics, including expression of stem cells markers such as SOX2 and ALDH1A and anchorage-independent growth." (PMID 29389895, 2018). "To further determine whether KDM3A epigenetically activates Sox2 expression to control ovarian cancer progression, we determined KDM3A and Sox2 protein expression in human ovarian cancer tissue array containing primary and metastatic ovarian cancer and adjacent normal tissues." (PMID 27694900, 2017). "Significant amount of KDM3A protein was detected on Sox2 promoter and KDM3A knockdown reduced KDM3A occupancy with concomitant increase in H3K9me2, indicating that KDM3A may epigenetically activates Sox2 expression to promote ovarian cancer stemness." (PMID 27694900, 2017). "Expression of SOX-2 has been investigated by immunohistochemistry analysis of normal ovarian epithelial, serous and mucinous cystadenoma and cystadenomacarcinoma specimens and LIN-28 was overexpressed in different epithelial tumors including breast, lung, colon and ovarian cancer." (PMID 27049920, 2016). "Furthermore, DAPT treatment decreased the effect of hypoxic treatment, and SOX2 knockdown decreased the effect of hypoxic treatment and NICD overexpression on sphere formation and drug resistance in established ovarian cancer cell lines and primary ovarian cancer cells." (PMID 27489349, 2016). "We found that exposure to M0, M1, or M2 macrophages for 48 hours did not significantly affect SOX2, OCT4, and NANOG expression in CAOV4 or OVCAR8 ovarian cancer cells." (PMID 39287565, 2024). "The primary ovarian cancer cells OvCa3 A were negative for one of either the CAF markers, PDGFRα, transcription factor Sox2, and CSCs marker CD133." (PMID 38791431, 2024). "Moreover, the correlations among Sox2, Survivin, and Class III β-tubulin have not been investigated among ovarian cancer." (PMID 26198101, 2015). "However, to our knowledge, to date, no comprehensive study has characterized SOX2, OCT4, and NANOG in the most commonly used ovarian cancer cell lines or determined whether their expression correlates with specific surface markers and other features of TICs." (PMID 33445692, 2021).
ovarian carcinoma (continued). "In addition, NOTCH1 signaling may mediate hypoxia signaling to induce SOX2 expression, and co-treatment with DAPT and paclitaxel resulted in decreased viability of both CSC- and non-CSC populations in ovarian cancer cells." (PMID 27489349, 2016).
squamous cell carcinoma (110 papers, 2010 to 2026). A carcinoma arising from squamous epithelial cells. "Histologically, Sox2-deficient mNCs resembled WT tumors, displaying features of poorly differentiated squamous cell carcinoma with abrupt keratinization, consistent with classic NC morphology." (PMID 41266112, 2026). "This correlation supports a prior report showing that NRF2 activation associates with SOX2 amplification in squamous cell carcinomas." (PMID 37716475, 2023). "Of note, CCAT1 has been linked to SOX2 as a coactivator in squamous cell carcinoma, and CCAT1 binds to epidermal growth factor receptor (EGFR) super-enhancer to stimulate EGFR expression by forming a complex with TP65 and SOX2." (PMID 33952719, 2021). "Notwithstanding, in non-small cell lung carcinoma (NSCLC), SOX2 overexpression was associated with a better prognostic course in only squamous cell carcinoma and both squamous cell carcinoma and adenocarcinoma." (PMID 32098209, 2020). "The other reason explains that NCI-H1703′s squamous cell carcinoma–basal cell cancer identity predisposes sensitivity to SOX2 downregulation as part of the response we saw for chelerythrine chloride treatments." (PMID 31935827, 2020). "on 146 NSCLC cases, squamous cell carcinoma (72%) expressed SOX2 much more than adenocarcinoma (8%), and the overexpression of SOX2 may be associated with a good prognosis for squamous cell carcinoma." (PMID 38800369, 2024). "It is likely that other factors influencing squamous cell carcinoma phenotype such as SOX2, which also appears as one of the top BRDT-associated factors, may be involved." (PMID 33658703, 2021). "Differences in biological properties of tumor-initiating cancer stem cells in squamous cell carcinoma compared to lung or breast adenocarcinoma have been suggested as an explanation to the different observed associations between SOX2 gene amplifications and prognosis." (PMID 26780934, 2016). "The transcription factors (TP63, SOX2) implicated in homeostasis of epithelial differentiation were found to be abnormally expressed in squamous carcinoma, and cell cycle, death, nuclear factor‐κB and other oncogenic pathways related to the development of squamous carcinoma." (PMID 32536035, 2020). "Despite this, approximately half of both Sox2 WT and knockout mice developed mNCs in the skin, with tumors exhibiting indistinguishable histology, consistent with poorly differentiated squamous cell carcinoma with abrupt keratinization." (PMID 41266112, 2026). "Histologically, Sox2-deficient tumors in the pancreas exhibited classic features of poorly differentiated squamous cell carcinoma, similar to Sox2 WT tumors." (PMID 41266112, 2026). "Coupled SOX2 overexpression in the context of NKX2‐1 deletion facilitates the formation of squamous carcinomas with oesophageal differentiation traits, though this is typically a transient stage or branch." (PMID 40847555, 2025). "In squamous cell carcinomas, it has been shown that SOX2 and P63 co-localize, interact, and co-regulate downstream genes such as ALDH3A1." (PMID 40643470, 2025). "Squamous cell carcinoma patients had substantially higher SOX2 and MAGE antibody expression than adenocarcinoma patients (P = 0.002 and P = 0.03, respectively)." (PMID 38800369, 2024). "The amplification and overexpression of SOX2 are recognized as hallmarks of squamous cell carcinomas originating from different tissue types." (PMID 38879516, 2024). "Other markers such as cortactin, NANOG, and SOX2 protein expression are frequent in squamous cell carcinoma." (PMID 36980171, 2023). "The 3q amplicon contains key oncogenic driver genes such as TP63, SOX2, PIK3CA, which are implicated in all squamous cell carcinomas, including ESCC." (PMID 37444412, 2023). "Knocking down PITX1’s DNA binding domain (DBD) significantly inhibited the growth of squamous cell carcinoma, with levels of Ki67 and EdU significantly decreasing, as well as decreased SOX2 expression, but KLF4 expression levels increasing." (PMID 37841446, 2023).
squamous cell carcinoma (continued). "Sox2 expression has been shown in several tumor types, such as lung, esophagus, breast, skin, prostate, and ovarian tumors, as well as in squamous carcinomas of various localizations and sarcomas." (PMID 37888115, 2023). "We found that USP13 altered lineage-determining factors such as NKX2-1 and SOX2 in club cells of the airway and reinforced the fate of club cells to squamous carcinoma development." (PMID 38093367, 2023). "PITX1 interacts with SOX2 to promote squamous cell carcinoma maintenance of tumor stem cells, increasing tumor malignancy." (PMID 37841446, 2023). "In contrast, PDPN expression, a demonstrated CSC marker in squamous carcinoma cells, while showing similar relationships with different TILs subtypes such as SOX2 and NANOG, was only significantly correlated with stromal and tumoral FOXP3+ cells." (PMID 34201050, 2021). "Although SOX2 and CCAT1 have already been implicated in squamous cell carcinoma, this is the first such finding in HCC." (PMID 33952719, 2021). "In contrast, Igfbp3 KO mice with NQO administration showed significantly increased numbers, volume, and burden of tumor nodules with SOX2 expression, a marker of squamous cell carcinoma." (PMID 33801272, 2021). "Some groups have recently suggested further molecular stem cell markers in squamous cell carcinoma, including SOX2, where, in particular, a co-expression of ALDH1 and SOX2 was found." (PMID 34307351, 2021). "For their part, SOX2 and SOX9 are stem factors that play an important role in the acquired resistance of squamous cell carcinoma (SCC) to cisplatin: the detailed mechanism of this feature is the switch from SOX2+ to SOX9+ mediated by SE remodeling." (PMID 34011395, 2021). "Since MYCT58A expression drove increased expression of the stem cell markers Lin28B, Lgr6, and Sox2 in this model, we also asked if the expression of these genes correlated in human squamous cell carcinomas." (PMID 32895364, 2020). "In non-small cell lung cancer (NSCLC), the amplification and subsequent overexpression of the SOX2 gene were common in both squamous cell carcinomas and adenocarcinomas (with higher expressions in squamous cell carcinomas compared to adenocarcinomas)." (PMID 32098209, 2020). "In the squamous cell carcinoma, the expression of Nanog (P = 0.005), SOX2 (P = 0.002), and OCT4 (P = 0.008) was significantly increased after IL-1β stimulation." (PMID 32547321, 2020). "Sox2, which is known to promote stemness of lung adenocarcinoma and is often amplified in squamous cell carcinoma, was expressed in these cells to varying levels." (PMID 32170113, 2020). "Gratifyingly, quantitative PCR indeed uncovered a notable reduction of NKX2-1 or SOX2 levels along with HDAC blockage in all tested lung adenocarcinoma or squamous cell carcinoma models, respectively." (PMID 31050342, 2019). "Here, we considered two additional scenarios, namely NKX2-1 in lung adenocarcinoma and SOX2 in squamous cell carcinomas." (PMID 31050342, 2019). "In fact, Sox2-driven models of squamous carcinomas are characterized by increased neutrophil recruitment, just as KL adenosquamous tumors displayed increased tumor associated neutrophils, while adenocarcinoma lesions did not48." (PMID 31519898, 2019). "The transcription factor SOX2 has been identified as a lineage survival oncogene in squamous cell carcinoma and copy number gain is a common event in several human malignancies including head and neck cancer." (PMID 29596469, 2018). "Recurrent gene amplification of the transcription factor SOX2 on human chromosome 3q is a common feature in the development of squamous cell carcinoma (SCC), but its function during carcinogenesis and prognostic value are highly context dependent." (PMID 29596469, 2018). "SOX2 amplification is a common event in squamous cell carcinomas of various organ sites, including lung, esophagus, cervix uteri, skin and penis." (PMID 30060526, 2018).
squamous cell carcinoma (continued). "SOX2 also plays a key role in the stem‐like cancer phenotype, particularly in squamous cell carcinoma." (PMID 28649742, 2017). "To avoid the confounding effect of SOX2 gene amplification in squamous cell carcinoma (SCC), and to focus on tumors with demonstrated involvement of NFATc2, we performed IHC analysis on 92 moderately to poorly differentiated AD." (PMID 28737489, 2017). "Amplifications of >5 copies were observed in 15 of 81 tumors with a SOX2 amplification, and SOX2 copy number alterations were most frequent in squamous cell carcinoma." (PMID 26780934, 2016). "SOX2 amplifications and overexpression have been reported as predictors of prolonged survival in squamous cell carcinomas." (PMID 26780934, 2016). "The pooling analyses revealed that there were significant associations between SOX2 DNA amplification and clinical features of NSCLC, gender, smoking status, squamous cell cancer (SCC) histology, and differentiations." (PMID 27150062, 2016). "TP63 has also been shown to be expressed in cervical cancer and interacts with SOX2 in squamous cell carcinomas we also stained for TP63 protein in parallel sections from the same biopsies." (PMID 25531390, 2014). "A gain in the 3q26 region, which contains the hTERC and SOX2 genes, is frequently observed in various squamous cell carcinomas of mucosal origin." (PMID 24410919, 2014). "In adult epithelial stem cells TP63 is a master regulator for the proliferative potential of these cells and interacts with SOX2 in squamous cell carcinomas." (PMID 25531390, 2014). "SOX2 amplification and overexpression is more common in squamous cell carcinomas (SCC) than in lung adenocarcinomas (ADC) and the prognostic impact of SOX2 overexpression in NSCLC appears to be dependent on the histologic subtype." (PMID 23620753, 2013). "Genes associated with squamous cell cancer, KRT5, cystatin A (CSTA) tumor protein p63 (TP63) and SOX2, were expressed at higher levels in ASC, but also expressed to some extent in the AC." (PMID 24324581, 2013). "Recently, amplification of the SOX2 gene locus has been described in squamous cell carcinoma (SCC) of different organ sites." (PMID 23544055, 2013). "In the present study, we found an association between the expression of Oct4 and lymphoid metastasis, whereas the expression of Sox2 was significantly related to the histological grade of individual hypopharyngeal squamous cell carcinomas." (PMID 20937145, 2010). "In conclusion, we demonstrated a vast increase in expression of the pluripotent stem cell related transcriptional factor, SOX2, in squamous cell carcinomas relative to adenocarcinomas of the lung." (PMID 20161759, 2010). "Similarly, high-risk HPV E6 and E7 oncoproteins enhance the CSC phenotype in squamous cell carcinomas by upregulating SOX2 and OCT4 stem cell transcription factors while simultaneously inhibiting cellular differentiation programs." (PMID 41157571, 2025). "SOX2 is often overexpressed in squamous cell carcinoma and small-cell lung cancer." (PMID 40115741, 2025). "Mollaoglu's study supports this notion, proposing that in the transformation from adenocarcinoma to squamous carcinoma, the deletion of NKX2‐1 or overexpression of SOX2 recruits tumour‐associated neutrophils, with the CXCL5 chemokine further promoting SOX2‐driven squamous cell transformation." (PMID 40847555, 2025). "It is reported that SOX2 antibody is expressed in different parts of squamous cell carcinoma." (PMID 38800369, 2024). "Besides, SOX2 is a lineage-specific oncogene that is widely amplified and overexpressed in various squamous cell carcinomas, including esophageal and head and neck squamous cell carcinomas." (PMID 38879516, 2024). "The regulation of YAP1 through Sox2 could be indirect in squamous cell carcinoma, as Sox2 antagonizes WWC1 to drive YAP1 activation." (PMID 36833308, 2023). "The high SOX2 expression was found in 50% of squamous cell carcinoma and 20.3% in adenocarcinoma." (PMID 37038139, 2023).